SATB1 (SATB homeobox 1)
Diseases named in the same sentence as SATB1 in open-access papers (continued):
Sharing a sentence is not in itself a finding about the gene and the disease.
breast carcinoma (continued). "In breast cancer cells, miR-488 downregulated SATB1 expression, and suppression of this miR resulted in SATB1-mediated EMT." (PMID 25874491, 2015). "In some studies, the expression level of SATB1 correlated with cancer progression and was suggested to be an useful prognostic marker in breast cancer, laryngeal squamous cell carcinoma, cutaneous melanoma, glioma, gastric, and hepatocellular cancer." (PMID 25874491, 2015). "Multivariate cox regression analyses showed that SATB1 and HER2 were independent risk factors for breast cancer patients, while HR was a protective factor for patients’ survival." (PMID 25956130, 2015). "SATB1 is reported to carry important weight to the progression of gastric cancer, cutaneous malignant melanoma, breast cancer, lung cancer, and lymphoma." (PMID 25956130, 2015). "Using immunohistochemistry (IHC) and fluorescence in situ hybridization (FISH), 169 patients with breast cancer were assessed for SATB1 expression, HER2 amplification and hormone-receptor (HR) expression." (PMID 25956130, 2015). "SATB1 is a relatively new prognostic parameter, and its significance in breast cancer is controversial." (PMID 24932280, 2014). "It has been shown that SATB1 was overexpressed in a variety of tumor types including breast cancer, laryngeal squamous cell carcinoma, gastric cancer, and malignant cutaneous melanoma." (PMID 24971456, 2014). "The miR-191/SATB1 functional link has been proposed to be helpful for prognosis and therapeutics of breast cancer." (PMID 24795757, 2014). "In order to analyze the effect of phosphorylation on SATB1 stability, we established breast cancer cell lines carrying empty vector, wild-type SATB1, SATB1S47A or SATB1S47D." (PMID 23762260, 2013). "In breast cancer cells, SATB1 coordinates the expression of a large number of genes to induce metastasis." (PMID 23642278, 2013). "In breast carcinoma, SATB1 regulates the expression of more than 1000 genes which are involved in 61 kinds of biological activity such as proliferation, apoptosis, DNA organization, electron transport, protein generation, receptor activity and so on." (PMID 23326301, 2013). "SATB1 has been reported to promote a metastatic phenotype and correlate with poor prognosis in breast cancer." (PMID 23379909, 2013). "SATB1 mRNA was highly expressed in a variety of cancers including breast cancer, ovarian cancer, prostate cancer as well as lymphoma." (PMID 23437226, 2013). "In human epithelium-derived carcinoma cells such as breast cancer cells, inhibition of SATB1 expression by siRNA or Decoy-DNA led to reversal of cell malignancy." (PMID 24047082, 2013). "SATB1 was originally characterized as a regulator in T cell differentiation, found to be overexpressed in metastatic breast cancer cell lines and in human tissue specimens from advanced stages of breast carcinomas with metastasis." (PMID 23379909, 2013). "Immunostaining of tissue arrays containing ∼1000 human breast cancer biopsies showed that high nuclear SATB1 staining correlated with patients' poor prognosis (P<0.0001)." (PMID 23251624, 2012). "The T-lineage enriched global chromatin organizer and epigenetic regulator Special AT-rich sequence-binding protein 1(SATB1) has been reported to promote a metastatic phenotype and correlate with poor prognosis in breast cancer." (PMID 22992394, 2012). "By immunohistochemical analyses, other studies have shown that high SATB1 expression correlates with metastasis of cutaneous malignant melanoma and gastric cancer, a finding consistent with SATB1's role in breast cancer metastasis." (PMID 23251624, 2012). "Forced expression of SATB1 in breast cancer cell lines, such as SKBR3, converts them to aggressive tumor cells." (PMID 23251624, 2012). "Conversely, silencing SATB1 expression by RNA interference in highly metastatic human breast cancer cell lines, such as MDA-MB-231 and BT549, abolishes their ability not only to metastasize, but also to form tumors in mice." (PMID 23251624, 2012).
breast carcinoma (continued). "For example the A/T-rich-DNA-binding protein SATB1 normally forms a specialized chromatin-silencing nucleoskeletal structure only in thymocytes; breast cancer cells with high SATB1 expression show grossly misregulated gene expression." (PMID 23029259, 2012). "1,318 breast cancer specimens were analyzed in the study and revealed a correlation between higher SATB1 expression levels and shorter overall survival times." (PMID 22839214, 2012). "Following this line of thought, recent observations have revealed that SATB1 expression is upregulated in multidrug-resistant breast cancer cells." (PMID 24212802, 2011). "Nuclear staining for SATB1 was also found to be of prognostic significance in a cohort of 1,318 breast cancer cases." (PMID 19642980, 2009). "Additionally, SATB1 expression gradually increased as breast tissues progressed from cystic hyperplasia to precancerous lesions, eventually reaching advanced breast cancer stages." (PMID 40071088, 2025). "miR-409 was found to regulate the biological behavior of breast cancer cells by targeting SATB1." (PMID 40071088, 2025). "The prognostic significance of SATB1 in breast cancer has been debated." (PMID 40071088, 2025). "However, SATB1 was initially defined as an oncogene because it is overexpressed in many malignancies, including breast cancer, colorectal cancer, prostate cancer, liver cancer, bladder cancer, and ovarian cancer." (PMID 39195213, 2024). "In TCGA breast cancers (n=1,089), PAM50 Luminal A (LumA), Luminal B (LumB), and Her2-enriched (Her2) breast cancer subtypes had the lowest expression of SATB1 relative to PAM50 Basal-like (Basal) and Normal-like (Normal) intrinsic subtypes (post hoc Wilcoxon adj." (PMID 39545637, 2024). "This variance in SATB1 implication for regulating cell processes spans from epidermal differentiation, breast cancer metastasis, thymocyte development, Th2 cell activation and cytokine production, cortical development, X-chromosome inactivation, and embryonic stem cell differentiation." (PMID 35812421, 2022). "Among these lncRNA LINC01016 regulates ERα, associated with survival and prognosis of breast cancer, LINC00578 showed association with lung cancer and pancreatic cancer, and LINC01016-miR-302a-3p/miR-3130-3p/NFYA/SATB1 axis was found to regulate endometrial cancer." (PMID 36072894, 2022). "Furthermore, previous study found that SATB1 contributed to multidrug resistance (MDR) phenotype in breast cancer cells." (PMID 33390772, 2021). "In addition, lncRNA H19 knockdown inhibits breast cancer cell proliferation and induces apoptosis by regulating miR-130a-3p/SATB1." (PMID 34081618, 2021). "Han and his groups reported that SATB1 upregulated the expression of MMP-9 in breast cancer." (PMID 33390772, 2021). "Furthermore, H19 acts as miRNA-130a-3p, sponge leading to upregulation of SATB1, thus promoting breast cancer progression." (PMID 34081618, 2021). "The studies have revealed that SATB1 may upregulate the expression of HER2 in various breast cancer cell lines and that SATB1 expression was correlated with HER2 amplification in breast cancer tissues." (PMID 31737131, 2019). "Furthermore, it has been suggested that breast cancer patients with SATB1/HER2 coexpression tended to have even worse prognosis than those with single positive expression." (PMID 31737131, 2019). "High SATB1 levels were related to the presence of lymph node metastasis and a higher TNM stage, two factors that are associated with a reduced life expectancy in breast cancer patients." (PMID 31450715, 2019). "Therefore, similar analyses were also performed to identify the differentially changed genes in breast cancer cells after knock-down of SATB1." (PMID 28147311, 2017). "Given that SATB1 is an oncogene which promotes breast tumor growth and metastasis, we were wondering if the downstream genes regulated by SATB1 are similar between esophageal cancer cells and breast cancer cells." (PMID 28147311, 2017).
breast carcinoma (continued). "It is unknown in esophageal cancer whether SATB1 has conserved or different function in regulation of the whole genomic transcriptome as in breast cancer." (PMID 28147311, 2017). "More recent studies are suggestive of adverse prognostic value for SATB1: significantly improved overall survival has been shown for homozygous SATB1 − 3600T/− 3363A/− 2984C haplotype carriers with expected lower SATB1 promoter activity in a cohort of breast cancer patients." (PMID 26512778, 2015). "Our study sheds light on SATB1 – a relatively new and less-explored biomarker in breast cancer." (PMID 26512778, 2015). "In breast cancer cell lines it has been proven that SATB1 could upregulate the expression of the HER2." (PMID 25956130, 2015). "Weak inverse correlation between SATB1 and ER (r = −0.27, p < 0.05) noted in our study may indeed suggest of possible differences of SATB1 role in HR-positive and HR-negative breast cancer." (PMID 26512778, 2015). "SATB1 expression was correlated with HER2 expression in breast cancer(r = 0.191; p = 0.013)." (PMID 25956130, 2015). "Also, miR-7 and miR-155 were shown to be involved in the posttranscriptional regulation of SATB1 gene expression in breast cancer cells." (PMID 25874491, 2015). "Altered SATB1 expression could be related to the occurrence and development of multidrug resistance phenotype in breast cancer." (PMID 25874491, 2015). "Moreover, results from studies on the prognostic value of mRNA levels of SATB1 have shown discrepant results in relation to its protein expression in e.g. breast cancer." (PMID 25323550, 2014). "SATB1 is found to be a switch to control tumor growth and metastasis of breast cancer and CRC." (PMID 24884732, 2014). "In addition, the expression of SATB1 has been found to correlate with diminished overall survival in breast cancer patients." (PMID 24932280, 2014). "Furthermore, multivariate survival analysis showed that SATB1 was an independent prognostic factor for breast cancer." (PMID 24971456, 2014). "Direct impact of SATB1 inhibition on tumor growth in breast cancer has been observed in vitro." (PMID 24932280, 2014). "SATB1 has high prognostic relevance in breast cancer patients." (PMID 24932280, 2014). "Current knowledge of the specific mechanisms of CRC metastasis is limited, however the function of SATB1 in progression and metastasis of breast cancer raises the possibility it may function in a similar manner in CRC." (PMID 23326301, 2013). "On the other hand, a recent study reported that miR-448 could target SATB1 and suppress its expression in breast cancer cells, and miR-448 was downregulated during epithelial–mesenchymal transition, an important process of tumor metastasis." (PMID 23642278, 2013). "Involvement of SATB1 in breast cancer has been shown also by independent studies." (PMID 23251624, 2012). "Furthermore, recent study indicated that SATB1 is an essential factor in the aggression of breast cancer, and SATB1 promoted tumor growth and metastasis of breast cancer by regulating the expression of hundreds of genes." (PMID 22815795, 2012). "However, another study from Pantani showed that the mRNA expression of SATB2 and SATB1 in human breast cancer were higher in malignant compared to normal breast tissue." (PMID 22815795, 2012). "In breast cancer, a role for SATB1 as being a master switch towards a metastatic phenotype and a marker of poor prognosis has been demonstrated in a study including immunohistochemical analysis of >1000 human breast cancer specimens." (PMID 22333599, 2012). "However, the findings of a recent study were in disagreement with previous results showing that SATB1 promotes metastasis in breast cancer." (PMID 24212802, 2011). "SATB-1 has been recently described as a gene responsible for breast cancer metastasis." (PMID 20691079, 2010). "In addition to its emerging physiological role, SATB1 expression has recently been found to contribute to breast cancer growth and metastasis." (PMID 19642980, 2009).
breast carcinoma (continued). "Multivariate analysis confirmed SATB1 to be an independent prognostic factor for breast cancer." (PMID 19642980, 2009). "In keeping with these results, we also found significantly higher levels of SATB1 mRNA in the breast cancer specimens compared to the background tissue and significant association with poor prognostic parameters including, increasing tumour grade, TNM stage and NPI." (PMID 19642980, 2009). "The research implicates SATB1 as a master regulator of metastatic competence in breast cancer." (PMID 19642980, 2009). "SATB1 was found to be expressed in both normal/benign breast tissue and breast cancer specimens." (PMID 19642980, 2009). "Furthermore, altering SATB1 levels could mitigate the effects of miR-409 on breast cancer cell proliferation and invasion." (PMID 40071088, 2025). "Together, these results suggest that SATB1-mediated genome organization may play a regulatory role in the maintenance of the luminal lineage and in the observed genome-wide dysregulation with age and breast cancer." (PMID 39545637, 2024). "Therefore, the association among SATB1, HER2 and HR in breast cancer is still confounded." (PMID 25956130, 2015). "Recent studies have identified several genes that under long-range regulation during breast cancer progression, including those encoding transcription factors such as ER, PR, AP1, AP2, FoxA1, GATA3, architectural components such as cohesion and SATB1, coactivators such as p300/CBP and SRC1-3." (PMID 26355959, 2015). "In addition to SCC9 cells, we also examined the role of plakoglobin in regulating SATB1 in MCF-7 and MDA-MB-231 (MDA-231) mammary epithelial cell lines, since SATB1 has previously been shown to play a major role in the regulation of breast cancer progression and metastasis." (PMID 24260116, 2013). "Furthermore, enforced expression of the miR-191/425 cluster in aggressive breast cancer cells altered global gene expression profiles and enabled us to identify important tumor promoting genes, including SATB1, CCND2, and FSCN1, as targets of miR-191 and miR-425." (PMID 23505378, 2013). "SATB1 may be an oncogene, which promotes the tumor growth and metastasis of breast cancer." (PMID 22815795, 2012). "Possibly, the prognostic value of SATB1 in breast cancer may depend on hormone receptor status." (PMID 22935204, 2012). "In an initial study on breast cancer, SATB1 was demonstrated to act as a genetic master switch towards a more aggressive tumour behaviour, and moreover, high immunohistochemical expression of SATB1 in tumours fom a large cohort of breast cancer patients was an independent marker of poor prognosis." (PMID 22935204, 2012). "Importantly, SATB1 may be necessary for the epigenetic transition and reorganization of the genome in breast cancer cells that become highly metastatic." (PMID 24212802, 2011). "Their presence in SATB1, previously linked to breast cancer promotion, and DDX26B, to our knowledge previously unreferenced in relation to breast cancer, provides further support for continued examination of the role of the genes in conjunction to breast cancer." (PMID 21698250, 2011). "Hence, expression of SATB1 could represent a singular event with profound implications for tumourigenesis and metastasis in human breast cancer." (PMID 19642980, 2009). "In cancers such as breast cancer and CRC, SATB1’s role in activating the Wnt/β-catenin signaling pathway has been associated with metastasis." (PMID 40071088, 2025). "More importantly, baicalein reduces SATB1 expression, downregulates Vimentin and Snail, and increases CDH1 levels, thereby inhibiting EMT and reducing distant metastasis in breast cancer." (PMID 40071088, 2025). "SATB1 directly upregulated HER2 expression, thereby enhancing the tumorigenic potential of breast cancer cells." (PMID 40071088, 2025).
breast carcinoma (continued). "To understand the role of SATB1 in regulating the aging biology of the luminal lineage, we explored 778 unique gene targets previously identified to be SATB1-activated and/or repressed in the MDA-MB-231 breast cancer cell line." (PMID 39545637, 2024). "Of note, SATB1 was also downregulated in PAM50 LumA, LumB, and Her2 breast cancer subtypes relative to their matched normal tissue and had the lowest expression in luminal subtype cancers—the subtype most associated with aging." (PMID 39545637, 2024). "As shown in the heatmap of the 20 TFs from the mRNA microarray, FOSL2, SATB1 and GATA6 in CAFs were identified as candidate transcription factors in the progression of angiogenesis in breast cancer." (PMID 33754039, 2021). "More specifically, SATB1 has been shown to be involved in the upregulation of EGFR (HER1), HER2, HER3, and HER4 in breast cancer cells." (PMID 33374770, 2020). "In human breast cancer cell line MDA-MB-231, the expression of EPS8 and CLDN1 genes depends on SATB1, and SATB1 binding sites have been found at multiple sites near and within genes encoding CLDN1 and EPS8 (based on our unpublished ChIP-seq results)." (PMID 31830989, 2019). "SATB1 is known to interact with miR-448, and the suppression of miR-448 increased SATB1 expression and induced EMT of breast cancer cells." (PMID 28793339, 2017). "Multivariate Cox regression analyses showed that SATB1, HER2 and HR were independent factors for survival rate in breast cancer." (PMID 25956130, 2015). "Previous studies have suggested that special AT-rich sequence-binding protein-1 (SATB1), which functions as a genome organizer, is crucial in the progression of breast cancer towards metastasis." (PMID 25586771, 2015). "But to our knowledge, little information has been available on the relationships among the expression of SATB1, HER2 and HR in breast cancer tissues so far." (PMID 25956130, 2015). "A miR-191 dependent repression of protein level was shown for NDST1 in MGC803s, CDK6 and SATB1 in human epidermal keratinocytes, and CCND2, CSDA, and EGR1 in the human breast cancer cell line MDA-MB-231." (PMID 25992613, 2015). "The effect of SATB1 and HER2 expression on breast cancer patients’ survival time was assessed by Kaplan–Meier method." (PMID 25956130, 2015). "In this paper, the relevance of SATB1 and HER2 expression was assessed in human breast cancer tissues, and their influence on tumor histological grade and patients’ survival was explored." (PMID 25956130, 2015). "SATB1 is known to directly regulate ERBB2, an important regulator of breast cancer progression, in MDA-MB-231 cells." (PMID 23251624, 2012). "These altered colony morphologies resembled the structures formed by aggressive breast cancer cell lines, MDA-MB-231 and BT549, which express a high level of endogenous SATB1." (PMID 23251624, 2012). "In this study, the level of mRNA expression of SATB1 and SATB2 were assessed in normal and malignant breast tissue in a cohort of women with breast cancer and correlated to conventional clinico-pathological parameters." (PMID 19642980, 2009). "In this study, the expression profile of SATB1 and SATB2 is assessed in a cohort of women with breast cancer." (PMID 19642980, 2009). "Notably, SATB1 was also found to act synergistically with HER2, an oncogene pivotal in breast cancer progression." (PMID 40071088, 2025). "further confirmed this finding, showing that SATB1 was abundantly expressed in breast cancer specimens but almost undetectable in normal and non-malignant tissues." (PMID 40071088, 2025). "SATB1 was found to be expressed in aggressive breast cancer cells, though firstly not present in human mammary epithelial cells." (PMID 35812421, 2022). "This suggests that SATB1 overexpression increases the size of the stem cell pool, and also activates Notch signaling pathways, increasing the expression levels of Snail1 and Twist1, which drive EMT in breast cancer cells." (PMID 25586771, 2015).